RN7SL650P (RNA, 7SL, cytoplasmic 650, pseudogene)
Gene: Miscellaneous RNA gene on chromosome 14 (21,429,508 to 21,429,806, reverse strand). Ensembl gene ENSG00000274475.
Homologues: Orthologues: chimpanzee Metazoa_SRP (98% identical), macaque Metazoa_SRP (95% identical). Paralogues in human: RN7SL1 (85% identical), RN7SL2 (85% identical), RN7SL3 (84% identical), RN7SL126P (83% identical), RN7SL147P (82% identical), RN7SL44P (82% identical), RN7SL220P (82% identical), RN7SL783P (82% identical), RN7SL145P (81% identical), RN7SL408P (81% identical), RN7SL444P (81% identical), RN7SL856P (81% identical), and 701 more.